CXCL16 (C-X-C motif chemokine ligand 16)
Description:
Acts as a scavenger receptor on macrophages, which specifically binds to OxLDL (oxidized low density lipoprotein), suggesting that it may be involved in pathophysiology such as atherogenesis (By similarity). Induces a strong chemotactic response. Induces calcium mobilization. Binds to CXCR6/Bonzo.
Synonyms: SR-PSOX; SRPSOX; CXCLG16
Tractability: Antibody: UniProt places it where antibodies can reach, with high confidence; its Gene Ontology location is reachable by antibodies, with high confidence; UniProt predicts a signal peptide or a membrane-spanning region.
Gene: Protein-coding gene on chromosome 17 (4,733,533 to 4,739,934, reverse strand). Ensembl gene ENSG00000161921.
Subcellular location: Cell membrane; Secreted
Subcellular location (Human Protein Atlas): Golgi apparatus; Vesicles; Predicted to be secreted
Pathways (Reactome):
Signal Transduction: Chemokine receptors bind chemokines; G alpha (i) signalling events
Gene Ontology:
Molecular function: chemokine activity; low-density lipoprotein particle receptor activity; scavenger receptor activity
Biological process: positive regulation of cell growth; positive regulation of cell migration; response to cytokine; response to tumor necrosis factor; response to type II interferon; chemotaxis; receptor-mediated endocytosis; T cell chemotaxis; lymphocyte chemotaxis
Cellular component: extracellular region; membrane; plasma membrane
Genetic constraint (gnomAD): Loss-of-function variants: 14 observed, 21.15 expected, observed/expected ratio (o/e) 0.66, 90% interval 0.44 to 1.03. The upper end of that interval is the gene's LOEUF score, 1.03, which puts it in group 4 of 6, group 1 being the genes least tolerant of losing a copy. Missense variants: 276 observed, 300.56 expected, observed/expected ratio (o/e) 0.92, 90% interval 0.83 to 1.01. Synonymous variants: 114 observed, 131.12 expected, observed/expected ratio (o/e) 0.87, 90% interval 0.75 to 1.02.
Homologues: Orthologues: chimpanzee CXCL16 (97% identical), macaque CXCL16 (81% identical), dog CXCL16 (57% identical), mouse Cxcl16 (47% identical), rat Cxcl16 (45% identical).
Diseases named in the same sentence as CXCL16 in open-access papers:
CXCL16 is named in the same sentence as 267 diseases in open-access papers, as found by Europe PMC text mining. Sharing a sentence is not in itself a finding about the gene and the disease. The quoted sentences say what the papers report.
breast carcinoma (57 papers, 2009 to 2026). "In the subtype-specific analysis, plasma CCL19 was associated with luminal A breast cancer, while CXCL16 was associated with HER-2-enriched breast cancer." (PMID 36685922, 2022). "In patients with breast cancer, cancer-associated fibroblasts have recently been shown to induce attraction and migration of cancer cells through secretion of CXCL16." (PMID 36078040, 2022). "It has been suggested that 12Gy radiation can significantly increase the secretion of C-X-C motif chemokine ligand 16 (CXCL16), which plays an important role in recruiting Th1 and cytotoxic T lymphocytes (CTLs) to all mouse and human breast cancer cells." (PMID 40765564, 2025). "In a 4T1 breast cancer model, using antibodies to neutralize intratumoral CXCL16 not only liberated CXCR6+ effector-memory cells from the primary tumor but also led to their accumulation as CD103+CD69+ TRM cells in the lungs." (PMID 40862776, 2025). "For example, anti-CXCL16 blockade in mouse breast cancer liberates CXCR6+ effectors from primary tumors, driving their migration and differentiation into lung TRM cells (see Section 3) and highlighting a promising target for TRM-directed therapies." (PMID 40862776, 2025). "Among these were the chemokines Cx3cl1, Cxcl16 and Ccl17, which were considered candidate chemotactic factors for breast cancer cells with mesenchymal properties." (PMID 38055067, 2023). "Similar pattern of CXCL16 up-regulation in myeloid cells was also observed by IF staining of CXCL16 of TNBC breast cancer with ddACT regimen." (PMID 37055410, 2023). "CXCR6, the receptor for CXCL16, is induced in breast cancer cells by hypoxia, and was found to be expressed in lymph metastasis from breast cancer patients." (PMID 38055067, 2023). "Radiations which are known to induce ICD stigmata also induce CXCL16 in human breast cancer cells and in diverse murine cancer cell lines." (PMID 36429101, 2022). "Our findings are clinically relevant, as VEGF, CXCL1, and CXCL16 mRNA expression is associated with OSM and/or OSMR levels in breast cancer patients and with decreased overall survival." (PMID 35192545, 2022). "Concerning CD8 T cells, it has been shown that irradiation induces CXCL16 production by breast cancer cells, thus allowing the migration and recruitment of CD8-activated T cells at the tumor site." (PMID 36429101, 2022). "In breast cancer cells, chronic hypoxia also increases the expression of CXCL16, although this is dependent on the CXCL10–CXCL16 loop." (PMID 33467722, 2021). "In breast cancer MDA-MB-231 cells, overexpression of CXCL16 causes apoptosis, while in diffuse large B-cell lymphoma, sCXCL16 promotes sensitivity to TNF-α-induced apoptosis." (PMID 33800554, 2021). "Irradiation induces the expression of CXCL16 in breast cancer cells, enhancing the migration of NK cells with high CXCR6 expression to kill tumor cells." (PMID 33763372, 2021). "An example of this is with ionizing radiation, as used in radiotherapy, which increases the expression of CXCL16 in the tumor cells, such as in colon carcinoma, breast carcinoma, fibrosarcoma, prostate carcinoma." (PMID 33800554, 2021). "In a mouse model of breast cancer, scientists found that IR markedly enhanced the secretion of C-X-C motif chemokine ligand 16 (CXCL-16), which binds to C-X-C motif chemokine receptor (CXCR6) on Th1 cells and activates CD8+ T cells." (PMID 33789758, 2021). "It is also postulated that the CXCL16→CXCR6 axis is involved in breast cancer brain metastasis due to high CXCL16 production by brain metastatic CAF." (PMID 33800554, 2021). "CXCL16 also plays an important role in enhancing the immune function of breast cancer by attracting T cell infiltration." (PMID 34512623, 2021). "The mRNA levels of CXCL16 are remarkably increased in breast cancer, prostate cancer, and colon cancer." (PMID 33489879, 2020).
breast carcinoma (continued). "Accordingly, the addition of a CXCL16 neutralizing antibody abolished the pro-tumoral stimulatory effects of conditioned medium derived from PDE5-overexpressing fibroblasts on breast cancer cell growth and migration." (PMID 31698786, 2019). "Herein, we show for the first time, that PDE5 is overexpressed in breast cancer stroma and plays an important role in pro-neoplastic features of activated fibroblasts through the secretion of CXCL16." (PMID 31698786, 2019). "CXCL16 induces the migration and invasion of the prostate cancer in vitro via CXCR6, which is increased in prostate and breast cancer cells and tumors, and is associated with aggressiveness and tumor stage." (PMID 29642534, 2018). "To further investigate the importance of chemokines CXCL12 and CXCL16 secreted by metastatic CAFs on breast cancer cell migration, we analyzed the expression of cognate chemokine receptors CXCR4 and CXCR6 on patient-derived cancer cells." (PMID 28649646, 2017). "For instance, CXCL16 released by irradiated breast cancer cells leads to the recruitment of effector T cells." (PMID 28267793, 2017). "CXCR6/CXCL16 has also been described as an oncogenic axis in a variety of solid cancers, such as papillary thyroid carcinoma, gastric, prostate, and breast cancer, through positive regulation of survival pathways such as ERK." (PMID 27585840, 2016). "In vitro and in vivo studies that overexpressed or downregulated CXCL16 were conducted in breast cancer cells." (PMID 24864132, 2014). "In this study, we show for the first time that upregulation of CXCL16 suppresses migration and invasiveness of breast cancer cells in vitro and delays progression of tumor growth in vivo." (PMID 24864132, 2014). "In this study, we determine the function of cellular CXCL16 as tumor suppressor in breast cancer cells." (PMID 24864132, 2014). "Our data suggest that the transmembrane CXCL16 is involved in breast cancer cells with important clinical significance." (PMID 24864132, 2014). "This inverse correlation between CXCL16 expression and migration or invasion suggested that CXCL16 play another role as tumor suppressor in inhibiting the migration and invasiveness of breast cancer cells." (PMID 24864132, 2014). "In summary, the current study demonstrated that cellular CXCL16 expression was negatively correlated with the migration and invasion of breast cancer cells." (PMID 24864132, 2014). "In this study, we explore the expression and function of CXCL16 in breast cancer cell lines that differ in aggressiveness." (PMID 24864132, 2014). "CXCL16 was induced in vitro in human breast cancer cells and murine mammary, prostate, and colon carcinoma cells by a single dose of 12 Gy." (PMID 23112958, 2012). "Induction of CXCL16 in mouse breast cancer cells was dose-dependent, starting at 2 Gy and reaching a plateau between 6 and 12 Gy." (PMID 23112958, 2012). "Disrupting this axis-for instance, by PFKP inhibition or CXCL16/CXCR6 blockade-may restore TA sensitivity in aggressive basal-type breast cancer, offering a promising strategy to improve long-term outcomes for hard-to-treat patients." (PMID 42024199, 2026). "CXCL16 plays a pivotal role in a variety of cancers, such as GC, glioblastoma multiforme, lung cancer, lymphoma, nasopharyngeal carcinoma, hepatocellular carcinoma, pancreatic cancer, and breast cancer, among others." (PMID 40452847, 2025). "The upregulation of CCR1 and CXCR6 and the downregulation of CXCR6 ligand (CXCL16) in cells other than MB-231, suggest that alternative chemokine-related axes may be involved in the trafficking of breast cancer cells to the bone marrow." (PMID 35158871, 2022). "Radiation-induced CXCL16 release by breast cancer cells attracts effector T cells." (PMID 35959371, 2022). "The heightened expression of CXCL16 by tumor cells is a common characteristic found in tissue from gastric and colon carcinoma patients, as well as in various mammary carcinoma cell lines." (PMID 33979626, 2021).
breast carcinoma (continued). "In this model, breast cancer cells secrete CXCL16 and MSC secrete CXCL10." (PMID 33800554, 2021). "CAF-derived CXCL16 could also promote brain metastases in breast cancer, which were significantly inhibited by the CXCL16 neutralizing antibody." (PMID 33414786, 2020). "CXCL12/CXCR4 and CXCL16/CXCR6 chemokine signaling also mediates breast cancer progression." (PMID 32879136, 2020). "The upregulation of C-X-C motif ligand 16 (CXCL16) in human breast cancer cells exposed to IR resulted in a systemic surge of C-C motif chemokine receptor 6 (CCR6), expressed in NK cells through CXCL16–CCR6 interaction, which was abrogated in the presence of an anti-CXCR6 Ab." (PMID 32612950, 2020). "Collectively, these results strongly suggest that increased stromal PDE5 may influence fibroblast phenotype and their effects on breast cancer cell growth and motility through CXCL16." (PMID 31698786, 2019). "Importantly, CXCL16 levels in breast cancer stroma showed a strong correlation with PDE5 levels and poor patient outcomes." (PMID 31698786, 2019). "Our findings indicated that PDE5 overexpression can activate stromal fibroblasts to produce and secrete CXCL16 that, in turn, may contribute to breast cancer progression by serving as a proliferative signal and as a regulator of motility." (PMID 31698786, 2019). "Indeed, as shown for stromal PDE5 levels, increased stromal expression of CXCL16 was found in breast cancer stroma compared to the corresponding normal tissue stroma and was associated with poor overall survival in Kaplan–Meier analysis." (PMID 31698786, 2019). "Through RNA-Seq and protein analyses, we found that cancer-associated fibroblasts derived from human breast cancer brain metastasis express significantly higher levels of chemokines CXCL12 and CXCL16 than fibroblasts from primary breast tumors or normal breast." (PMID 28649646, 2017). "Utilizing our hydrogel assay system, patient-derived breast cancer cells were treated with a receptor-blocking antagonist directed against CXCR4 alone or in combination with neutralizing antibody directed against CXCL16 and tested for cancer cell migration to brain metastatic CAF aggregates." (PMID 28649646, 2017). "The expression of CX3CL1 and CXCL16 was confirmed on protein level by immunocytochemistry, which revealed high expression for the brain tumor cell lines and low expression for the breast carcinoma cell line MCF-7." (PMID 26796342, 2016). "IHC staining of CXCL16 in a tumour tissue microarray consisting of 144 human breast cancers showed that high fibroblast expression of CXCL16, correlated significantly to TN breast tumours (P=0.010), while CXCL16 expression in the malignant cells per se did not." (PMID 27725631, 2016). "Similarly, radiation induced CXCL16 expression stimulated the recruitment of antitumor CD8 + cells in a murine model of breast cancer." (PMID 26021984, 2015). "Targeting of cellular CXCL16 expression is a potential therapeutic strategy for breast cancer." (PMID 24864132, 2014). "Since EGFR overexpression is common in breast cancer, the impact of CXCL16 alteration on proliferation may be masked by EGFR overexpression or other genetic alterations." (PMID 24864132, 2014). "Meanwhile, to determine whether CXCL16 gene silencing would affect breast cancer progression, MCF-7 cells highly expressive for CXCL16 underwent stable knockdown of CXCL16 using shCXCL16, scrambled shRNA (shNC), or liposomes only (mock)." (PMID 24864132, 2014). "Importantly, CXCL16 induction by local radiotherapy with two doses of 12 Gy was also seen in vivo in the mouse 4T1 mammary carcinoma, and shown to enhance tumor infiltration by CXCR6+ effector CD8 T cells." (PMID 23112958, 2012). "However, in certain cancer types like renal cell carcinoma and breast cancer, CXCL16 may also reduce cancer cell proliferation." (PMID 40452847, 2025). "Also in breast cancer cells, high CXCL16 expression is found in less aggressive cell lines." (PMID 33800554, 2021).
breast carcinoma (continued). "The breast cancer cell lines are attracted through chemokines CXCL16 and CXCL12 by fibroblasts that are associated with BCBM and therefore, blocking receptor-ligand interaction of CXCR6-CXCL16/CXCR4-CXCL12, which may be preventive therapy for BCBM." (PMID 34944840, 2021). "Therefore, high levels of PDE5 and CXCL16 can be detected in breast tumor stroma and their stromal expression may predict poor outcome among breast cancer patients." (PMID 31698786, 2019). "The role of CXCL16 varies across malignancies; for instance, CXCL16 and its receptor CXCR6 are upregulated in breast cancer but downregulated in renal cell carcinoma." (PMID 39409924, 2024). "In summing up, d-MAPPS augmented T cell-driven immune response to murine mammary carcinoma by enhancing DC-based generation of Th1 and Th17 cells and by increasing cytotoxicity of CD8+ CTLs in CXCL16- and IL-27-dependent manner." (PMID 35757015, 2022). "CXCL16 expression is increased in MDSC by factors secreted by cancer cells, as shown in mammary carcinoma 4T1 cells." (PMID 33800554, 2021). "Upregulation of CXCL16 in renal cell carcinoma ACHN3 cells, breast cancer MDA-MB-231 cells, prostate cancer DU145 and PC3 cells reduces the migration of these cells." (PMID 33800554, 2021). "High levels of CXCL12 and CXCL16 in CAFs from human brain cancer metastasis attract breast cancer cells via the CXCR4/CXCL12 and CXCR6/CXCL16 pathways." (PMID 33096815, 2020). "In a previous study, irradiation was reported to induce CXCL16 chemokine expression in cancer cells and to enhance the migration of CXCR6+ natural killer cells to breast cancer cells for their destruction." (PMID 31715586, 2019). "In summary, this is the first report demonstrating the expression of both CXCL16 and CXCL12 in CAFs derived from human breast cancer metastasis in the brain." (PMID 28649646, 2017). "Further corroborating our findings, we found that mRNAs for CXCL16 as well as for IL8, CSF2, MMP9, EDN1 and CCL2 all were expressed at significantly higher levels in basal-like breast cancers as compared with luminal A tumours." (PMID 27725631, 2016). "Expression of CXCL16 was evaluated in mammary epithelial cell MCF-10A and in three breast cancer cell lines: SK-BR-3, MCF-7, and MDA-MB-231." (PMID 24864132, 2014). "Consistent with previous reports, we found that CXCL16 and CXCR6 were coexpressed in breast cancer cells but to inverse extent." (PMID 24864132, 2014). "In contrast, in MDA-MB-231 breast cancer cells, overexpression of CXCL16 did not affect proliferation." (PMID 33800554, 2021). "To assess the effect of oestrogen deprivation on chemokine gene expression in ER+ MCF-7 breast cancer cells, we used RT-qPCR to measure the mRNA expression of chemokines CCL5, CCL22, and CXCL16 from nine biological replicates from three independent experiments." (PMID 34602068, 2021). "Moreover, CAFs derived from human breast cancer brain metastasis show higher expression of CXCL12 and CXCL16 in comparison with healthy fibroblasts and CAFs from primary breast tumors." (PMID 33096815, 2020). "More importantly, our results showed a significant association between the expression levels of PDE5 and CXCL16 in the stroma of breast cancer patients and a statistically significantly poorer overall survival in patients with high PDE5 and high CXCL16 levels compared with all other patients." (PMID 31698786, 2019). "More relevantly, treatment with the CXCL16 neutralizing antibody was able to significantly abolish the stimulatory effects exerted by CM derived from PDE5-overexpressing MEFs on both growth and motility of MCF-7 breast cancer cells." (PMID 31698786, 2019). "As previously shown for stromal PDE5, CXCL16 expression did not significantly correlate with breast cancer molecular subtypes, lymph node status, grade, ER, PR, and HER2 positivity." (PMID 31698786, 2019). "Moreover, CXCL16 via interaction with CXCR6 is capable of increasing cell migration, invasion, and metastasis in breast cancer." (PMID 31698786, 2019).